CXCL13 (C-X-C motif chemokine ligand 13)
Diseases named in the same sentence as CXCL13 in open-access papers (continued):
Sharing a sentence is not in itself a finding about the gene and the disease.
infection (continued). "Furthermore, patients who succumbed to infection produced high CXCL13 and had a higher ratio of nucleocapsid to RBD antibodies." (PMID 33472985, 2021). "In addition, CXCL1, CXCL2, and CXCL5 suppress excess CXCL13 expression in macrophages via the CXCR2 axis during the early infection stage." (PMID 34868067, 2021). "Since a positive correlation between CSF CXCL13 levels and symptom duration could be very interesting, as this stresses the role of CSF CXCL13 as an early marker for infection, this should be investigated further in a prospective study." (PMID 34132584, 2021). "Similarly, CCL19, CCL22, and CXCL13 were significantly upregulated by a primary infection in the R line of the HSF flock when compared to its S line counterparts." (PMID 30678719, 2019). "Chemokines such as CXCL8 and CXCL13 can recruit immune cells to the site of infection." (PMID 31656701, 2019). "Indeed in mouse lymphoid tissue specifically the homeostatic chemokines CCL19, CCL21 and CXCL13 were downregulated after infection with several different pathogens leading to altered homing, positioning and priming of lymphocytes within the LN61." (PMID 29379035, 2018). "We measured CXCL13 levels in plasma by enzyme linked immunosorbent assay (ELISA) and found significantly higher levels in individuals with bNAbs at 6 months post infection (p = 0.002) but not at later time points." (PMID 29630668, 2018). "Analysis of mRNA expression in pooled DRG revealed that expression of mRNA encoding CXCL13 was significantly elevated at 2 and 4 weeks following B. burgdorferi administration, while levels of CCL2 mRNA were higher at 4 weeks following infection." (PMID 28202084, 2017). "However, CXCL13 levels trended toward being higher upon infection and were significantly higher at 90 DFOPV compared to baseline despite complete suppression of viral loads in most of the individuals." (PMID 28943879, 2017). "In contrast, changes in BAFF and CXCL13 during hyperacute infection were not directly associated with viral loads." (PMID 28943879, 2017). "Importantly, pre-infection samples allowed longitudinal tracking of changes following infection, clearly demonstrating that CXCL13 is induced following infection." (PMID 28943879, 2017). "However, individuals with high plasma levels of CXCL13 early in infection were more likely to have detectable but weak cross-neutralizing antibodies at 1 year PI." (PMID 28943879, 2017). "In fact, upon infection the induced-expression of CXCL13 together with other chemokines, such as CCL21 and CCL19, could be indispensable to induce ectopic GC development." (PMID 26771137, 2016). "Increased CXCL13 expression from day 1 post infection preceded increased CCL19 and CCL21." (PMID 24847941, 2014). "Thus, it is understandable that CXCL13 levels in the CSF of LNB patients increase early in the course of the infection before any detectable antibody production, and CXCL13 in CSF has been suggested to be an early marker of LNB." (PMID 24920219, 2014). "Interestingly, both CXCL-13 and CXCR5−/− mice are equally susceptible to infection with either Mtb H37Rv or Mtb HN878 described here, implicating IL-17-independent pathways in CXCL-13 induction during Mtb H37Rv infection." (PMID 24831696, 2014). "CXCL13 appears redundant, as infection of CXCL13-deficient mice does not affect CNS accumulation of CD19+ B cells, leaving CXCL10 as a likely candidate to recruit SINV-specific ASC to the CNS." (PMID 23435240, 2013). "In response to TLR ligands as an indicator of infection or tissue damage, MZ B cells can move into the B-cell follicles and may eventually exit the spleen and migrate to other tissues in response to CXCL13." (PMID 22936933, 2012). "Therefore, CXCL13 is not only restricted to the acute phase of inflammation, but as seen in the example of tertiary lymphoid structures in MS or neuroinfectious diseases, it also seems to be involved in chronic inflammation and the humoral phase of infection." (PMID 38203597, 2023).
infection (continued). "Furthermore, in IL-10-/- BMDMs derived from IL-10-/- mice, the CXCL13 protein concentration was significantly decreased compared that in wild-type BMDMs after FMDV infection (FMDV-Wild type group vs. FMDV-IL-10-/- group: 2158.0 ± 257.7 vs. 1175.1 ± 113.7 pg/mL, respectively, n = 3, p < 0.05)." (PMID 37047294, 2023). "Together, interactions among multiple molecules consisting of this network, such as CD19, CD 22, and CD79A/B, and chemokines including CCL19, CCL22, and CXCL13 may contribute to enhanced immune responses in the resistant line in the HSF flock to the innate infection." (PMID 30678719, 2019). "We demonstrate that aprepitant treatment attenuates B. burgdorferi-induced elevations in CCL2, CXCL13, IL-17A, and IL-6 gene expression in dorsal root ganglia, spinal cord, and/or cerebrospinal fluid of rhesus macaques at 2 to 4 weeks following intrathecal infection." (PMID 28202084, 2017). "However, higher levels of CXCL13 and not B cell changes or viremia during hyperacute infection were found to be associated with emergence of cross-neutralizing antibodies within 1 year of infection." (PMID 29250072, 2017). "ENA-78 is primarily known for the chemotaxis of neutrophil, particularly during the early stages of infection, and moreover, ENA-78 is indirectly involved in B-cell chemotaxis via CXCL13." (PMID 38932217, 2024). "CXCL13 and CXCL12 protein levels in whole lung homogenates were measured using ELISAs at various time points after Sp19F infections." (PMID 38715601, 2024). "During disease state such as infections or COPD, iBALT can develop and recruits B cells by producing the chemokine CXCL13 that attracts the CCR5-expressing B cells." (PMID 36936934, 2023). "CXCL13 and CCL19 mRNAs at these times were then measured by RT-qPCR, and throughout RVFV MP12 infection, relative expression (normalized to GAPDH) of these chemokines continued to increase, suggesting progressive activation of the noncanonical NFκB pathway." (PMID 37515252, 2023). "Downregulation of the CXCL1/2/5-CXCR2 axis, as demonstrated in the CXCL5-/- infection mouse model and the CXCR2 blockade model, enhanced CXCL13 expression in infected lungs as soon as during the innate immunity stage." (PMID 34868067, 2021). "The chemokine CXCL13 and its receptor, CXCR5, play a central role in driving humoral immunity during infection and vaccine responses." (PMID 34746181, 2021). "Nevertheless, MIG/CXCL9, IP-10/CXCL10, I-TAC/CXCL11, BLC/CXCL13 and JE/MCP-5/CCL2 detected in kidney of C3H-HeJ mice at 24h post infection was also detected in serum/blood cells in our study." (PMID 34249775, 2021). "CXCL13 and its receptor CXCR5 (which was downregulated in the probiotic group) also play important roles in infection, inflammation, and the immune response." (PMID 33668643, 2021). "We also detected a progressive reduction in the expression of LTα, CXCL13 and its receptor, CXCR5, along the course of infection." (PMID 34804009, 2021). "In conclusion, smaller B cell follicles together with reduced expression of IL-23, CXCL13 and CCL19 indicate that ELS formation in response to H37Rv infection is impaired in the male lung." (PMID 32198367, 2020). "Plasma levels of CXCL13 have been reported to be elevated during chronic HIV-infection, however there is limited data on such elevation during early phases of infection and on the effect of ART." (PMID 30846990, 2019). "In the present study, using the mouse model, which has been widely accepted as an infection model for elucidating the interaction between PCV2 and host, the anti-apoptotic role of the CXCL13 protein was evaluated in PCV2-infected splenocytes in vitro." (PMID 30819249, 2019). "These cells are responsive to CXCL13 by their CXCR5 receptor and they travel to follicles after infection in a CXCL13-dependent manner." (PMID 24762633, 2014). "Expression of the B cell chemoattractants CXCL13, CCL19 and CCL21 increased progressively post infection." (PMID 24847941, 2014).
infection (continued). "We recently reported that C. trachomatis induces expression of CXCL13, the ligand for CXCR5, in human fallopian tube tissue following infection." (PMID 23189125, 2012). "We propose that RSV infection may activate the CXCL13/CXCR5 axis, leading to the recruitment of B cells to the site of infection and exacerbating mucosal damage through an enhanced humoral immune response." (PMID 41360931, 2025). "We did observe a trend for increased CXCL13 in participants with prior infection, although this was not statistically significant." (PMID 37573434, 2023). "Finally, in a model of infection with Salmonella, resident macrophages expressing CXCL13 and CX3CR1 promote the infiltration of B and CD4+ T cells in areas of infection, where they are activated, giving rise to TLS induction." (PMID 37622111, 2023). "Since CXCL13 and CCL19 have been shown to be transcribed specifically during activation of the noncanonical NFκB pathway, mRNAs of these chemokines were measured at multiple timepoints following RVFV MP12 infection." (PMID 37515252, 2023). "BLC/CXCL13 on the other hand, is a small homeostatic CXC family chemokine that is highly expressed in the pleural cavity and critically involved in B-cell recruitment during infection." (PMID 34540715, 2021). "As CSF CXCL13 levels decline rapidly after successful antibiotic therapy for LNB, this marker can be used to distinguish an active LNB infection from a previous, cleared infection." (PMID 34132584, 2021). "As the infection progresses, the expression of CXCL1/2/5 decreases and in turn upregulates the expression of CXCL13 by macrophages, monocytes, and DCs, which contributes to B lymphocyte accumulation in the infected lungs during the late infection and recovery stages." (PMID 34868067, 2021). "Mabuka and colleagues showed that plasma levels of B- cell activation factor (BAFF) increased after 7 days from the onset of HIV-1 viremia and declined at 14 days, whereas, plasma levels of CXCL13 were elevated at day 7 from the onset of HIV-1 viremia and increased throughout the infection period." (PMID 33732259, 2021). "Critically, infection of mice deficient in CXCR5, the cognate receptor for CXCL13, did not experience increased C. rodentium bacterial burden or pathology." (PMID 30973939, 2019). "Amongst cytokines, the genes for Cxcl9, Cxcl10, Cxcl13, Il-1β, Il-6, Tnf, Tnfsf10, IFN-γ, Ccl2, Ccl4, Ccl7, Ccl17, and Mif were highly up-regulated (ranging from 2- to 405-fold, p ≤ 0.05), whereas Cxcl12 and Cxcl14 were down-regulated during in vivo infection." (PMID 30857242, 2019). "Our analysis indicates that Cxcl13 but not Ccl8 expression is induced beginning 10 days p.i. until day 30 p.i., a period during infection that closely mirrors when the number of ChAT+ T-cells increased in the colon." (PMID 30973939, 2019). "However, plasma levels of CXCL13 during early infection, the effect of ART on CXCL13 secretion, and the contribution of CXCL13 to HIV disease progression and systemic immune activation are poorly understood." (PMID 30846990, 2019). "After early infection with Mtb, lung parenchyma (both resident immune cells and non-immune cells) express CXCL13." (PMID 24762633, 2014). "A previously published study from our laboratory however, reported down-regulation of IL-12p40, IL-8, IL–1β, and CCL-20 mRNA in tracheal tissues at day-1 post-infection, whereas chemokines like MIP-1β, CXCL-13, RANTES and lymphotactin were found to be up-regulated." (PMID 25401327, 2014). "This regimen did not produce any statistical difference in the course of infection between the groups although we noted that anti-CXCL13 treated mice cleared infection a few days earlier than controls." (PMID 23189125, 2012). "Similarly, the mobilization of peritoneal B-1 cells to mucosal sites of infection is stimulated by TLR ligands and depends on a robust migratory response to the chemokine CXCL13." (PMID 22936933, 2012).
infection (continued). "Finally, there was a group of cytokines and chemokines: TNF, IFNγ, CCL5, CXCL9, CXCL10 and CXCL13, which were early after infection elevated in the vaccinated but not detectable in the naive animals, suggesting an adaptive immune response as the trigger." (PMID 39472590, 2024). "Moreover, expression of chemokines associated with the homing of lymphocytes to the infected lung such as CXCL13 and CCL19 was significantly lower in males compared to females, further indicating that B cell follicle formation in response to H37Rv infection is impaired in males." (PMID 32198367, 2020). "Importantly, we found higher levels of CXCL13 during hyperacute infection in individuals who subsequently developed detectable cross-neutralizing antibodies within 1 year of infection compared to those who did not." (PMID 28943879, 2017). "In the absence of infection and during normal immune responses, CXCL13 and its receptor CXCR5 are involved in the homing of B-cells and follicular B-helper T cells into primary follicles in lymph nodes and spleen, and in germinal center formation and lymphoid organogenesis." (PMID 25879435, 2015). "The B cell chemoattractant, CXCL13 was dramatically lower in aged as compared to juvenile animals, regardless of infection status whereas CXCL12 and CCL20, known dendritic cell (DC) chemoattractants, were much higher in mock and SARS-CoV infected aged animals (unpaired student T-test)." (PMID 24642138, 2014). "We evaluated UGT (uterine horns+oviducts) pathology in mice treated with anti-CXCL13 Ab and Cxcr5−/− mice by examining inflammatory scores in the UGT from hematoxylin and eosin stained slides and fibrosis from trichrome stained slides of oviducts after infection." (PMID 23189125, 2012). "Later, at the time when iBALT was fully formed in wild-type mice, we could not detect any differences in CXCL13 levels, suggesting that the instructive signals that condition the lung for clustering adaptive immune cells are given very early (2–4 dpi) after infection." (PMID 27579026, 2016). "Therefore, levels of CXCR3 (receptor for CXCL9 and CXCL10), CXCR5 (receptor for CXCL13), CCR5 (receptor for CCL3 and CCL5), and CCR7 (receptor for CCL19) were analyzed on CD45hiCD11bloCD19+ B cells which infiltrated the brain at 7, 14, 30, and 60 days post infection." (PMID 27207308, 2016). "Six months post-infection, the levels of both CCL-3 and CXCL-13 were not elevated in either hospitalized or non-hospitalized individuals." (PMID 38646483, 2024). "Re-exposure to pneumococcus 1 week after initial infection stimulates the CD4+ cell-dependent accumulation of activated, proliferative EV B cells in a manner that is independent of CD40L and CXCL13." (PMID 38715601, 2024). "However, very high levels of CSF CXCL13 are not specific for LNB and can be found in other infections such as cryptococcal meningitis, neurosyphilis, and AIDS." (PMID 39766248, 2024). "CXCL13/BLC has been previously shown to be an effective plasma biomarker for increased germinal center (GC) activity in mice, non-human primates, and humans in immunization and infection models." (PMID 35061851, 2022). "We found that the majority of CD11b+ LyChi Ly6G- CD64+ inflammatory monocytes present in the ear of VACV-infected mice at 5 days post-infection were CCR5+, the receptor for CCL4, rather than CCR2+, or positive for the receptors for CXCL13 (CXCR5) or CXCL9 and CXCL10 (CXCR3)." (PMID 31603920, 2019).
infectious disease (10 papers, 2015 to 2025). A disorder directly resulting from the presence and activity of a microbial, viral, or parasitic agent in humans. "Therefore, we measured selected circulating cytokines, such as CXCL13, previously shown to reflect germinal center activation in lymph nodes in clinical and preclinical models of autoimmune and infectious diseases, as well as circulating Tfh." (PMID 34618687, 2021). "Based on the crucial roles the CXCL13:CXCR5 axis plays in both physiologic and pathologic immunity, it is not surprising that this axis has been implicated in the pathogenesis of a number of infectious diseases." (PMID 31354634, 2019). "It is clear that the CXCL13:CXCR5 axis is intimately involved in the initial and chronic phases of HIV infection, and, considering the central role this axis plays in humoral immunity, it is not surprising that CXCL13 has been implicated in the pathogenesis of several other infectious diseases." (PMID 31354634, 2019). "Moreover, the CXCL13 not only exhibits chemotactic activity depending on CXCR5 but also acts regulatory roles in chronic inflammation, infectious diseases, autoimmune disorders, neurological conditions and tumors." (PMID 40264781, 2025). "Clinicians should be aware that high levels of CXCL13 are not found exclusively in LNB but also in other infectious diseases of the CNS." (PMID 25975424, 2015). "Clinicians should be aware that high levels of CXCL13 are not found exclusively in LNB but in various infectious diseases of the CNS." (PMID 25975424, 2015).
neurological diseases (10 papers, 2013 to 2024). "Looking at CSF of patients with neurological diseases, CXCL13 was the cytokine most closely linked to B cell recruitment to the CNS and intrathecal Ig synthesis." (PMID 34868008, 2021). "Based on these published findings, we suggest that CXCL13 has high diagnostic utility and may be applied in laboratory diagnostics as a potential diagnostic marker in human spirochetal neurologic diseases." (PMID 32331231, 2020). "Since CXCL13 has been reported to facilitate lymphocyte recruitment to the CNS and increased levels of CXCL13 have been found in various neurological disorders, we investigated the level of the chemokine in our mice." (PMID 36157272, 2022). "It is known that CXCL13 plays a functional role in the development of various neurological diseases." (PMID 32331231, 2020). "CXCL13, a member of the chemokine family, is the major determinant for B cell recruitment to the intrathecal compartment during a range of human neurological disorders." (PMID 33161894, 2020). "Our retrospective cross-sectional study aimed to investigate the diagnostic capacity, treatment response, and value for the severity of CSF-CXCL13 in different neurological diseases to provide an overview, especially for clinicians, of what an increase in CXCL13 may indicate." (PMID 38203597, 2023). "Moreover, increased immunoreactivities for GFAP and Iba1 and elevated levels of CXCL13 and CCL12, the chemokines involved in central leukocyte recruitment and other neurological diseases, were also observed in the brain." (PMID 36157272, 2022). "The serum gradients of CXCL13 are higher in NMO patients within 2 months of symptom relapse than in noninflammatory neurological disease controls." (PMID 28413701, 2017). "To rule out the possibility that patients without focal CNS lesions harbor elevated CXCL13 or CXCL9 CSF levels, we also used archived CSF samples from 101 patients with various non-lesional neurological diseases as historical controls (for diagnoses)." (PMID 33841320, 2021).
adenocarcinoma (8 papers, 2014 to 2025). A common cancer characterized by the presence of malignant glandular cells. "Patients with adenocarcinomas with high CXCL13 infiltration also showed a trend toward improved RFS (median survival of 52 months for the low infiltration group vs. not reached), although the results were not significant (HR: 0.3697 [95% CI: 0.1067, 1.281])." (PMID 41514638, 2025).